CYP11B2 (cytochrome P450 family 11 subfamily B member 2)
Diseases named in the same sentence as CYP11B2 in open-access papers (continued):
Sharing a sentence is not in itself a finding about the gene and the disease.
tumor (continued). "Another study showed a correlation between increased A/CPA tumor volume and increased CYP11B1 expression, along with decreased CYP11B2 expression." (PMID 39010034, 2024). "IHC staining and western blot analyses revealed that both the A/CPA and pure APA tumor tissues were positive for CYP11B1, CYP11B2, and CYP17A1, implying that these tumors can produce both aldosterone and cortisol." (PMID 29770148, 2018). "Notably, several key genes involved in steroid synthesis, including CYP11B2, CYP21A2, and HSD3B2, were significantly upregulated along the trajectories toward the tumor cell lineage." (PMID 40190189, 2025). "Immunohistochemical analysis showed that the tumor cells were positive for P450scc, P450c17, P450c21, and CYP11B1; faintly positive for DHEA sulfotransferase (DHEA-ST); and negative for CYP11B2; confirming the cortisol-producing ability of the tumor." (PMID 39430734, 2024). "Utilizing this technique, we sequenced DNA from the CYP11B2 positive tumor and CYP11B2 negative adjacent normal tissue and demonstrated the presence of somatic KCNJ5 mutation p.I157S in the tumor and not the adjacent normal area." (PMID 36051386, 2022). "In CYP11B2 staining, APMs have a strong uniform immunoreactivity for CYP11B2, without evident neoplasia or hyperplasia." (PMID 35813615, 2022). "The CYP11B2 immunoreactivity adjusted for tumor area was not correlated with serum cortisol (r = 0.158, p = 0.097) or PRA (r = −0.168, p = 0.073)." (PMID 34631800, 2021). "CYP11B2 DAB score multiplied by tumor area correlated positively with PAC and U-Aldo and negatively with serum potassium level." (PMID 33061968, 2020). "Of these seven patients, six had APAs with intratumor heterogeneity, with five tumors having distinct CYP11B2-positive and CYP11B2-negative tumor regions." (PMID 30456751, 2018). "Recent clinical observations have revealed predominant expression of HSD3B2 mRNA and protein in tumor cells of aldosterone-producing adenoma (APA), and HSD3B1 mRNA significantly correlated with CYP11B2 mRNA levels and plasma aldosterone concentrations in APA patients." (PMID 27057163, 2016). "One patient with a CYP11B2-negative tumor had multiple APCCs." (PMID 29899838, 2018). "The tumor cells were positive for CYP11B1 and negative for CYP11B2, consistent with the findings of a CPA." (PMID 40568364, 2025). "The tumor cells were partially positive for CYP11B1 and negative for CYP11B2, which was consistent with the findings of CPA." (PMID 40568364, 2025). "Interestingly, aldosterone production may occur from multiple sources: multiple aldosteronomas in the same adrenal gland, dominant non-producing adenoma with satellite CYP11B2 positive non-dominant nodules, and clusters of autonomous aldosterone-producing cells (APCCs) without apparent neoplasia." (PMID 35813615, 2022). "Further immunostaining with adrenocortical enzymes revealed that all these tumor components were CYP11B1 positive and CYP11B2 negative, indicating cortisol-producing tumors." (PMID 35660748, 2022). "(iii) APCCs express CYP11B2, but not CYP11B1, whereas APAs consist of heterogeneous tumor cells expressing either CYP11B2 or CYP11B1." (PMID 27721827, 2016).
cardiovascular disease (16 papers, 2012 to 2025). "It is important to note that there have been discrepant results with the CYP11B2 −344T>C variant and its association with aldosterone secretion and the presence of cardiovascular disease." (PMID 23936266, 2013). "In recent years, the aldosterone synthase CYP11B2 has been investigated as a potential therapeutic target for the treatment of different cardiovascular diseases." (PMID 36293446, 2022). "This newly pathway of CYP11B2 SNPs/aldosterone/cardiovascular disease opens new research insights and therapeutic avenues for the cardiovascular diseases." (PMID 25102047, 2014). "The simultaneous inhibition of CYP19 (aromatase) and CYP11B2 should reduce the levels of both oestrogen and aldosterone thus having the desired anti-cancer and anti-cardiovascular disease effects." (PMID 23291110, 2013). "Aldosterone synthase (CYP11B2) is a promising therapeutic target for the treatment of cardiovascular diseases related to abnormally high aldosterone levels." (PMID 23133610, 2012). "Since CYP11B2 is the crucial enzyme in the production of aldosterone, dual inhibition of CYP17/CYP11B2 is proposed to reduce the risks of cardiovascular diseases in PCa patients." (PMID 23880851, 2013). "Similarly, many genes, including CALM2, PDCD4, TXNIP, CYP11B2, P2Y12, and ROCK1, have been identified as downstream targets of GAS5 in cardiovascular diseases." (PMID 38812041, 2024). "Human aldosterone synthase (CYP11B2) and cortisol synthase (CYP11B1) have been exploited in inhibitor screening campaigns to identify treatments for cardiovascular disorders and cortisol-related diseases, which affect specific cellular responses to compounds for drug development." (PMID 38036976, 2023).
renal disease (7 papers, 2006 to 2026). "Among RAAS candidate genes, angiotensinogen (AGT), angiotensin II type I receptor (AGTR1), angiotensin-converting enzyme (ACE), and aldosterone synthase (CYP11B2) genes appear to be particularly relevant to renal disease." (PMID 24977181, 2014).
psychiatric disorder (1 paper, 2019). A disorder characterized by behavioral and/or psychological abnormalities, often accompanied by physical symptoms. "We then examined methylation in a shortlist of genes that were previously associated with early life stress and psychiatric disorders as well as placental functioning: Ank3, Avp, Avpr1a, Avpr1b, Bdnf, Cacna1c, Cyp11b1, Cyp11b2, Fkbp5, Hsd11b1, Igf2, Morc1, Nr3c1, Oxt, Oxtr, Pclo, Slc6a4." (PMID 30655507, 2019).
CYP11B2 also shares sentences with these, for which no sentence is quoted: essential hypertension (11 papers); cancer (6); chronic kidney disease (6); cardiomyopathy (3); aortic atherosclerosis (2); fibrosis (2); hypoaldosteronism (2); Hyponatremia (2); metabolic disease (2); Neurologic Abnormalities (2); renal failure (2); Acidosis (1); adrenal cancer (1); adrenal crisis (1); autosomal dominant disease (1); breast carcinoma (1); cerebrovascular disease (1); congestive heart failure (1); diabetic nephropathy (1); diastolic heart failure (1); dilated cardiomyopathy (1); endothelial dysfunction (1); epilepsy (1); familial hyperaldosteronism type II (1); gestational hypertension (1); glomerulosclerosis (1); glucocorticoid deficiency (1); Hyperglycemia (1); hypertensive heart disease (1); idiopathic dilated cardiomyopathy (1).
A further 20 diseases each share a sentence with CYP11B2 in 1 paper.